EPCAM (epithelial cell adhesion molecule)
Diseases named in the same sentence as EPCAM in open-access papers (continued):
Sharing a sentence is not in itself a finding about the gene and the disease.
cancer (continued). "Another platform for CTC detection is AdnaTest (Adnagen AG) that enriches CTCs using a cocktail of antibodies (e.g., EpCAM, MUC-1, AR, Her2) specific to the cancer type (e.g., breast, lung, prostate, ovarian) followed by a subsequent analysis of tumor associated gene expression by RT-qPCR." (PMID 34026650, 2021). "In vitro cytotoxicity assay further confirmed their lytic activity against NK cell-resistant, EpCAM-positive cancer cells, but not to EpCAM-positive normal cells, demonstrating the retained tolerability of the CAR-iNK cells towards normal cells." (PMID 34802459, 2021). "In contrast, the majority of other cancers express EpCAM at levels much higher than normal non-cancerous controls." (PMID 34957124, 2021). "The CellSearch immunocapture method is therefore currently limited to epithelial type cancers and not applicable to non-epithelial cancers such as sarcomas, lymphomas and neural tumours which do not express EpCAM." (PMID 33652649, 2021). "In addition to CD29 and CD98, we also decided to test the following antigens, due to their known functions that make them candidates to be widely expressed on the cancer cell lines: CD47, B2M, and Epithelial cell adhesion molecule (EPCAM)." (PMID 33690223, 2021). "Thus, EpCAM demonstrates a dynamic and context dependent role during EMT and cancer initiation and progression." (PMID 34209658, 2021). "Some evidence that metformin reduces EPCAM expression exists from in vitro studies of cancer cells, but to our knowledge it has not previously been shown in humans that circulating EPCAM is associated with metformin." (PMID 33279861, 2021). "It has been noted that even the CellSearch system, established as CTC detection method for some kinds of cancer, may miss CTCs undergoing epithelial-to-mesenchymal transition (EMT) because of the dependency on expression of the epithelial marker EpCAM." (PMID 34064720, 2021). "By examining the expression pattern of cancer stem cells markers (e.g., PROM1, CD44, and EPCAM), it is found that CD44 positive population may render drug resistance in HCC272." (PMID 34105295, 2021). "Most conventional approaches for capturing CTCs use an EpCAM-based enrichment strategy, but it is limited to cancers displaying low or no EpCAM expression, including RCC." (PMID 35052770, 2021). "Moreover, in recent years utility of aptamers has also been demonstrated to detect EVs from cancer cells by capturing the cells through aptamers targeting CD63, EpCAM, PDGF-β receptor or nucleolin." (PMID 35056102, 2021). "Furthermore, LR004-VC-MMAE treatment also significantly reduced the expression of various cancer stemness marker genes, including Oct4, Sox2, KLF4 and EpCAM." (PMID 34879870, 2021). "Epithelial cell adhesion molecule (EpCAM) is often used as a target for CTC enrichment because it is widely expressed on the cell surface of cancer cell-derived CTCs and has not been detected on normal blood cells." (PMID 33777749, 2021). "In addition, EpCAM, CD45, and Y chromosome-positive circulating cancer hybrid cells were detected in PDAC patients whereby high cell numbers were correlated with a poor survival." (PMID 34503305, 2021). "Such cytotoxicity was antigen dependent as no obvious killing was found against EpCAM-negative cancer cell lines MCF7 and HTB129." (PMID 34802459, 2021). "Most mesenchymal tissues and cancers have minimal or no detectable EpCAM expression, while high EpCAM expression is frequently present in epithelial cancers." (PMID 34209658, 2021). "Hence, endocytosis and membrane recycling are means of regulation of EpCAM protein levels during differentiation of ESC and EMT induction in carcinoma cells." (PMID 34693227, 2021).
cancer (continued). "In contrast, AS906 and AS914, which derived from carcinomas with sarcomatoid features and formed loose spheroids in culture, expressed ZEB1, SNAI2, CD44, and Vimentin, but negligible levels of EpCAM and E-Cadherin (CDH1)." (PMID 33941777, 2021). "EpCAM displays spatiotemporal patterning during embryogenesis, tissue morphogenesis, cell differentiation, and epithelial-to-mesenchymal transition (EMT) in carcinomas." (PMID 34693227, 2021). "CSCs drive cancer initiation, progression, metastasis, recurrence and drug resistance, and express Nanog, CD133, CD90, SOX2, EpCAM, CD44, Klf4 and Oct4, some of which may functionally support liver CSC phenotypes like invasiveness and chemoresistance." (PMID 33343368, 2020). "The breast EPCAM-negative carcinoma was considered noninformative due to the inconsistent expression of EPCAM in this type of cancer." (PMID 33003511, 2020). "Alternative methods, such as surface-enhanced Raman spectroscopy-based biosensors, have been suggested to trace EpCAM expression in cancer cells during EMT, but they have not been tested for CTC detection yet." (PMID 32764280, 2020). "As a result, classical cancer markers such as epithelial cellular adhesion molecule (EpCAM) and inflammation markers were not identified in our EAC samples." (PMID 32650561, 2020). "EpCAM, TROP2, claudins, matriptase, and HAI proteins have all been reported roles in cancer." (PMID 32326212, 2020). "Since we used chromosomal instability as an inclusion criterion to identify DCCs, our findings do not apply to claudin-low cancers, which are derived from EpCAM−, chromosomally stable cells." (PMID 33020483, 2020). "Although EpCAM-based methods allow the identification of CTCs from epithelial cancers, many CTCs detected in patients with different cancers do not have sufficient epithelial characteristics (i.e., there is a lack of or low expression of EpCAM)." (PMID 32764280, 2020). "Cells do not express epithelial markers, including EpCAM or cytokeratins, during epithelial-to-mesenchymal transition (EMT) associated with cancer progression and intravasation of cancer cells." (PMID 33327605, 2020). "The most commonly used antibody is EpCAM, but several chips employ a cocktail of antibodies specific to a particular cancer or use anti-CD45 and/or anti-CD66 antibodies for negative depletion (retaining of leukocytes and eluting CTCs)." (PMID 32708837, 2020). "Importantly, higher expression of stemness genes including interleukin (IL)-6, EpCAM and CD24 was observed in HCC with lnc-DILC downregulation, indicating a positive correlation between lnc-DILC downregulation and increased cancer stemness properties." (PMID 32231294, 2020). "By analyzing a cohort of 904 cancer patients from the METABRIC, TCGA database, who underwent RT, it was found that patients with higher than mean value of EpCAM expression show significantly (P = 0.0307) inferior overall survival than those with lower EpCAM level." (PMID 33490064, 2020). "There is substantial literature regarding the role of EpCAM and TROP2 in cancer." (PMID 32781650, 2020). "CD44 is another common marker to identify CSCs in various cancer types, similar to CD133 and EpCAM." (PMID 32391048, 2020). "Notably, higher EpCAM and/or CD133 levels were shown to predict poor survival in various cancers, such as colon, prostate, lung and breast cancer." (PMID 32408542, 2020). "EpCAM is involved in the regulation of cancer cell adhesion, proliferation, migration, invasion, stemness, and epithelial-to-mesenchymal transition (EMT) during cancer progression." (PMID 32764280, 2020).
cancer (continued). "The epithelial cell adhesion molecule (EpCAM)-dependent technique was approved by the U.S. Food and Drug Administration (FDA) in 2004, and represents the “gold standard” for CTC isolation in different cancers, including CRC." (PMID 32858879, 2020). "On the other hand, all normal control subjects were negative for EpCAM expression, which reflects its high specificity among the cancer patients." (PMID 32212818, 2020). "Moreover, together with epithelial cell adhesion molecule (EpCAM), CD133, CD90, CD24, and CD13, CD44 was also characterized as a cancer stem cell (CSC) marker." (PMID 31991677, 2020). "Many scFvs have been generated against known proteins overexpressed by a number of different kinds of cancer cells, such as HER and EpCAM, or against target proteins that are essential for cancer growth and spreading, such as VEGF (involved in neo-angiogenesis)." (PMID 32184825, 2020). "Once we confirmed that our strategy can be employed into identify EpCAM positive and EpCAM negative expressed cancer cells, we then moved on to establish a syngeneic model using two cancer cells, for in vivo validation and metastasis monitoring." (PMID 32923313, 2020). "In accordance to our findings, in a previously published report, PD-L1 was highly expressed in epithelial (EpCAM positive) CTCs regardless of the type of cancer and was co-expressed with mesenchymal markers in NSCLC CTCs." (PMID 33322610, 2020). "The negative selection-based CTC isolation scheme features the capability to harvest viable, label-free CTCs, particularly all possible CTCs, including conventionally defined EpCAM+ CTCs and EMT-transformed cancer cells, from the blood samples of cancer patients." (PMID 32903713, 2020). "The wide distribution of EpCAM expression on most cancer cells indicates that it is not a specific marker of CSCs." (PMID 32493501, 2020). "The epithelial cell adhesion molecule (EPCAM/CD326) is a 39–42 kDa transmembrane glycoprotein almost exclusively expressed in epithelial tissue and epithelial-derived cancers and functions not only in cellular adhesion but also signaling, migration, proliferation and differentiation." (PMID 33027913, 2020). "CTCs have also been detected by the expression of combined epithelial markers such as EPCAM and cytokeratin (CK), which are expressed on normal epithelial cells and carcinomas but are absent on blood leukocytes." (PMID 33081135, 2020). "Today, EpCAM is reckoned as a multi-functional transmembrane protein involved in the regulation of cell adhesion, proliferation, migration, stemness, and epithelial-to-mesenchymal transition (EMT) of carcinoma cells." (PMID 32507912, 2020). "In treated rat carcinomas, we found significant caspase-3, Bax, and Bax/Bcl-2 expression increases; on the other side, a significant down-regulation of Bcl-2, Ki67, CD24, ALDH1, and EpCam expressions and MDA levels." (PMID 33375383, 2020). "The most commonly employed CTC detection methods rely on the presence of epithelial cell adhesion molecule (EpCAM), which is expressed on most carcinoma cell surfaces, but not on GBM cells." (PMID 32650387, 2020). "Furthermore, EpCAM is regulated during EMT and is itself a regulator of this trans-differentiation program in carcinoma and stem cells." (PMID 32507912, 2020). "All clones displayed EpCAM profiles that were distinct from the parental population (80:20), highlighting the phenotypic plasticity and stochastic EMP processes that exist in subpopulations of cancer cells." (PMID 31234417, 2019). "EpCAM is considered to be a CSC marker, since its intracellular part EpICD mediates anchorage and growth factor independent cell proliferation, which is a typical trait in cancer." (PMID 31726709, 2019). "ofCS is present on cancer cell types independent of origin or disease stage, meaning it exists on EpCAM-negative and EMT CTCs as well." (PMID 31053984, 2019).
cancer (continued). "Moreover, these drugs either diminish or induce expression of CAM, like EpCAM or CD82, which were altered through cancer initiation, progression and metastasis." (PMID 30289336, 2019). "EpCAM is an attractive target for CTC isolation because it is detectable on the majority of epithelial-derived cancer types and not detectable on leukocytes, making it possible to isolate CTCs effectively from other blood components." (PMID 31053984, 2019). "EpCAM is identified as a CSC marker and a potential therapeutic target for cancer." (PMID 31324239, 2019). "When the EpCAM antigen is targeted, there are CTCs that cannot be identified and under extreme conditions, there is no antigen specific for all cancers." (PMID 31416266, 2019). "EpCAM is frequently upregulated in carcinomas but is not expressed in cancers of non-epithelial origin." (PMID 31443698, 2019). "However, some cancer cells undergo an epithelial-mesenchymal-transition (EMT), resulting in the downregulation of EpCAM and some cytokeratins." (PMID 30774772, 2019). "Interestingly, in both models, the expressions of various cancer stem cells (CD44, CD90, CD133, and EpCAM) were also decreased." (PMID 30858465, 2019). "Cancer cells can biochemically alter their phenotype, undergoing epithelial to mesenchymal transition (EMT), gaining invasive mesenchymal and stem cell-like properties and losing epithelial characteristics, such as cell surface EpCAM expression." (PMID 31053984, 2019). "The only FDA approved system, CellSearch® is an EpCAM based method, although EpCAM is a conventional marker expressed by cancer cells of epithelial origin it is not expressed by all CTCs." (PMID 31281432, 2019). "In contrast, the negative method enabled isolation of cancer cells from blood samples with an average recovery rate of 83.1%, irrespective of the expression level of EpCAM." (PMID 31181790, 2019). "Five additional proteins were studied: carcinoma stem cell markers: TRA-1-60, CD326 (epithelial cell adhesion molecule, EpCAM), galectin-3 (GAL-3), the immune checkpoint inhibitor CD274 (programmed cell death ligand-1, PD-L1) and carcinoma marker pan-keratin (cytokeratins)." (PMID 31527554, 2019). "Fortunately, Shigdar and the co-authors designed a kind of RNA aptamer EpDT3, which is the first aptamer specifically recognizing the cancer stem cell marker EpCAM with no immunogenicity or toxicity." (PMID 29467932, 2018). "To conclude, we analyzed the influence of CPEB1 on cancer stemness in HCC cells by analyzing self-renewal ability, chemoresistance, metastasis and expression of the stem cell-related genes OCT4, NANOG, SOX2, LIN28, CD24, EpCAM and CD133." (PMID 30237545, 2018). "To validate that in the heterogeneous primary cultures, cytokine induction was due to response of the cancer cells and not the stromal cells, we separated cells positive for the epithelial marker EpCAM from the EpCAM‐negative counterparts." (PMID 29741811, 2018). "Although expressed by most cancer cells, EpCAM is not confined to malignant cells but also found on normal epithelial cells." (PMID 30380648, 2018). "This was theorized to be because the high affinity meant that the antibodies were binding to all EpCAM expressing cells, not just the highly expressing cancer cells." (PMID 30586898, 2018). "Surprisingly though, increased EpCAM expression does not always suggest poor prognosis for patients, and it is very much context-driven due to the distinct biology that some subtypes of cancer have." (PMID 29329202, 2018). "To date, most of studies for CTC isolation determine the CTCs using 4 panels, DAPI, CK, CD45 and EpCAM, regardless of type of cancers." (PMID 30315187, 2018). "In line with this, we demonstrate that the rVAR2-enriched CTC population from cancer patients contains vimentin-positive cells as well as EpCAM-negative cells, indicating that the rVAR2 isolates include mesenchymal-like subpopulations." (PMID 30115931, 2018).
cancer (continued). "So, why has EpCAM, which is expressed on the vast majority of cancers of epithelial origin, failed to deliver on the initial promises of forty years ago?" (PMID 29329202, 2018). "Similar to CK-based detection, positive EPCAM expression is not a sufficient criterion to consider a cell a cancer cell." (PMID 30211312, 2018). "There are many differences between metastatic and non-metastatic cancer cells, and one of them is the EpCAM expression level." (PMID 30424286, 2018). "These strategies are prone to disregard tumour cells from (i) cancers of non-epithelial origin like melanoma, and (ii) cancers with downregulated EpCAM expression." (PMID 29662054, 2018). "SE-iFISH platform improved the sensitivity of CTCs detection regardless of cancer heterogeneity, down-regulation or absence of CKs and EpCAM." (PMID 30454007, 2018). "We conclude that EGF-induced RIP of EpCAM is neither a common nor a frequent mechanism in carcinoma cell differentiation along the EMT." (PMID 30261040, 2018). "Using the maintrac® approach, carcinoma-derived cells can be detected without enrichment among the other blood cells due to the surface expression of EpCAM (epithelial cell adhesion molecule) specific for epithelial cells." (PMID 30380648, 2018). "EGF treatment also did not foster the formation of EpICD in whole-cell lysates or in cytoplasmic and nuclear extracts of Kyse30 and HCT8 cells, so we conclude that EGFR-dependent RIP of EpCAM is not a common process in carcinoma cells." (PMID 30261040, 2018). "For an in vitro assessment of the self-renewal capacity of cancer stem cells, HT-29 cells were treated with the EpCAM aptamer-survivin siRNA chimera or negative control chimera, followed by further incubation in the presence or absence of 2 μM 5-FU for 5 days." (PMID 28724889, 2017). "BsAb which targets EpCAM and CD3 prolonged the contact time between lymphocytes and cancer cells." (PMID 28931402, 2017). "The dissemination of EMT positive cells is an important feature of cancer metastatic progression and these cells, negative for epithelial markers (CK, EpCAM), would have been missed by epithelial marker based approaches." (PMID 29263843, 2017). "Experimental results showed that culturing cancer cells on chitosan increased cell motility, drug resistance, quiescent population, self-renewal capacity, and the expression levels of stemness and CSC marker genes, such as OCT4, NANOG, CD133, CD44, and EpCAM." (PMID 28367998, 2017). "Moreover, CRC7.4 had high-level expression of CD133, a cancer stem cell (CSC) marker, as well as other CSC markers such as CD44 and EpCAM." (PMID 29173894, 2017). "Interestingly, several previously identified EOC cancer stem cell (CSC) markers, including CD44, CD24, CD117 (Kit), and EpCAM, were up-regulated in ID8-P1 vs. ID8-P0 cells." (PMID 29163813, 2017). "Primary HCC tissues are known to be composed of a variety of EpCAM+/− and CD90+/− cancer cells." (PMID 28900199, 2017). "This method is unable to capture CTCs of all cancer types, however, because some CTCs are known to be EpCAM negative." (PMID 28640869, 2017). "No specific marker is uniformly expressed by all cancer types, and EpCAM is not an ideal biomarker for CTCs detection as the variation of its gene expression." (PMID 29132396, 2017). "MOC31 binds the epithelial cell adhesion molecule (EpCAM), a transmembrane glycoprotein with high expression in carcinomas, including HGSOC, and with low expression in nonmalignant tissues." (PMID 28977905, 2017). "When epithelial cell adhesion molecule-1 (EpCAM), also named TROP-1 or TACSTD1, is overexpressed, this could be considered a prognostic biomarker for several carcinomas and CS." (PMID 28531111, 2017). "However, the BiTE antibody against EpCAM and CD16 recruited innate immune cells and then induced effective ADCC, as well as enhanced the killing of human carcinoma overexpressing EpCAM." (PMID 28931402, 2017).